ZEB2 (zinc finger E-box binding homeobox 2)
Diseases named in the same sentence as ZEB2 in open-access papers (continued):
Sharing a sentence is not in itself a finding about the gene and the disease.
tumor (continued). "In contrast, it has already been reported that ZEB2, which is one of the first identified miR-200 family targets, promotes tumour metastatic potential and correlates with a poor prognosis for human CRC." (PMID 31623346, 2019). "This suggest that the regulation of Zeb2 expression is probably subjected to different mechanisms in these two tumor subtypes." (PMID 30087437, 2019). "(iv) The direct correlation observed between the abundance of the NR2F1 and ZEB2 mRNAs in human tumor samples when using coexpression matrix analyses." (PMID 30087437, 2019). "And then, we detected that expression level of ZEB2, a transcription factor related to tumor metastasis, was regulated by UCA1 in GC cells." (PMID 30464170, 2018). "Further studies of the functions and mechanisms of ZEB2 depending on the tumor progression stage are warranted." (PMID 29416649, 2018). "MVD in tumors from mice injected with ZEB2-suppressed cells was significantly lower than in those from mice injected with control cells, suggesting that ZEB2 induces tumor angiogenesis in vivo." (PMID 29416649, 2018). "Along with ZEB1, ZEB2 is reported to localize to the cytoplasm as well as to the nucleus, and the subcellular localization of ZEB2 is regulated in normal and tumor tissues, suggesting that ZEB2 functions are regulated by means of its subcellular localization." (PMID 29416649, 2018). "The HIF-1α–ZEB2–ephrinB2 axis is an important regulatory pathway in promoting tumor invasiveness and evasive resistance in glioma during bevacizumab treatment." (PMID 29560266, 2018). "Our study suggests a direct association between ZEB2 expression and tumor angiogenesis; the ZEB2-Sp1 collaboration directly induces VEGF expression to stimulate endothelial cell activation and tumor angiogenesis." (PMID 29416649, 2018). "MiR-200c is a regulator of epithelial-to-mesenchymal transition which targets the transcriptional repressors of E-cadherin, ZEB1 and ZEB2, suggesting a tumor suppressive function." (PMID 30473751, 2018). "TUNEL staining of tumor sections showed that the level of apoptosis in tumors from mice injected with ZEB2-suppressed cells was significantly higher than that in tumors from mice injected with control cells." (PMID 29416649, 2018). "It is possible that Sp1 modulates/enhances the nuclear presence of ZEB2, which can contribute to the accelerated aggressiveness of malignancy and tumor progression." (PMID 29416649, 2018). "Since ZEB2 is also expressed by stromal cells, to specifically address the involvement of ZEB2 in human tumor cells we sought to use an in situ approach." (PMID 29666469, 2018). "While some of the molecular mechanisms that control levels of both of the ZEB proteins have been documented, there are now new tumour suppressor candidates implicated in the control of ZEB1 and ZEB2." (PMID 29963231, 2018). "At the new tumour site de-repressed E-cadherin facilitates cell adhesion, and then inhibition of ZEB2, leads to reduced Vimentin and lowered invasive capabilities resulting in a stable secondary tumour." (PMID 29963231, 2018). "Previously, we observed that nuclear expression of ZEB2 is higher in tumor cells than in normal cells, suggesting nuclear localization/transport of ZEB2 during tumor progression." (PMID 29416649, 2018). "This is also consistent with our PDX data where increasing expression of ZEB1/ZEB2/SNAI1 leads to lower tumor initiating capacity suggesting that a terminal mesenchymal phenotype has the lowest tumor initiating frequency." (PMID 29162812, 2017). "Many of the EMT inducing transcription factors such as Snail1, Snail2/slug, ZEB1, ZEB2, FOXC2 and TWIST1 have been associated with tumor invasion and metastasis." (PMID 29202800, 2017).
tumor (continued). "A dual-luciferase reporter assay system and chromatin immunoprecipitation further confirmed that FOXO1 suppresses tumor cell invasion and metastasis mainly through direct binding to the ZEB2 promoter." (PMID 27924058, 2017). "Several studies proved the relationship between E-Cadherin, β-catenin, snail, ZEB1, ZEB2 expression and tumor budding using immunochemistry, and drew the conclusion of EMT induction at the tumor–host interface, but more evidence are required." (PMID 27999192, 2017). "Loss of E‐cadherin expression during EMT is induced by ZEB1 and ZEB2 enabling tumour cells to dissociate from the tumour mass, invade local tissues and metastasise to distant sites." (PMID 28133913, 2017). "EMT, a well-characterized embryological process, has been identified to play a critical role in tumor metastasis, which is characterized by losing epithelial markers (e.g. E-cadherin), and acquiring of mesenchymal markers (e.g. N-cadherin, ZEB2)." (PMID 28186964, 2017). "The Mes‐Inf tumours were negative for a large number of basal cell‐related and SCC‐related cytokeratins, but positive for tumour‐cell expression (IHC) of both ZEB2 and VIM." (PMID 28195647, 2017). "In ccRCC cells, it appears miR-30a-5p modulates tumor cell migration and invasion through regulation of ZEB2." (PMID 28569782, 2017). "The basal/SCC‐like tumour samples also expressed ZEB2 and VIM, but only in surrounding stromal cells." (PMID 28195647, 2017). "As ZEB2 directly binds to the E-cadherin promoter and strongly inhibits E-cadherin expression, ZEB2 promotes tumor cell invasion and metastasis." (PMID 27924058, 2017). "Instead, the tumour cells were themselves mesenchymal‐like and expressed the typical mesenchymal genes ZEB2 and VIM, indicating a tumour type that has undergone epithelial–mesenchymal transition (EMT)." (PMID 28195647, 2017). "Our networks showed a group of conserved associations between the miR-200 networks inferred from tumour and control data, this association core is conformed by miR-200 miRs and known transcription factors such as: TWIST-1, TWIST-2, ZEB-1 and ZEB-2." (PMID 29051564, 2017). "Zeb1 and Zeb2 have been shown to regulate the expression of various EMT- and tumor related genes and thereby have been implicated in EMT, tumorigenesis and metastasis." (PMID 27588490, 2016). "Taken together, our results identify ZEB2 as an attractive therapeutic target to inhibit tumour invasion and counteract tumour resistance mechanisms induced by anti-angiogenic treatment strategies." (PMID 27470974, 2016). "The loss of p63 results in the downregulation of tumor suppressive miR-205, causing upregulation of ZEB1 and ZEB2, which in turn, suppresses E-cadherin." (PMID 27588490, 2016). "Taken together, our data show that the ZEB2 induction and downregulation of ephrinB2 are important prerequisites of tumour invasion in evasive resistance." (PMID 27470974, 2016). "Mechanistically, hypoxia-inducible factor (HIF)-1α induces the EMT repressor ZEB2, which directly downregulates ephrinB2 through promoter binding to enhance tumour invasiveness." (PMID 27470974, 2016). "To further validate that the ephrinB2 downregulation following ZEB2 induction functionally regulates evasive resistance to bevacizumab treatment we generated G55 tumour cells with constitutively elevated ephrinB2 levels." (PMID 27470974, 2016). "We observed that miR-203 overexpression modulated expression of EMT and tumor stemness factors including suppression of ZEB2, N-cadherin, NANOG, c-MYC, and BMI1 as well as induced E-cadherin expression." (PMID 27589832, 2016). "Consistently, bevacizumab treatment markedly elevated the expression of ZEB2 at the tumour rim concomitantly with increased invasiveness." (PMID 27470974, 2016). "In NPC tumor spheres, we observed decreased miR-203 expression and increased ZEB2 expression compared to their parental NPC cells." (PMID 27589832, 2016).
tumor (continued). "We next examined ZEB2 expression as well as other tumor stemness factors in tumor spheres compared to standard culture conditions." (PMID 27589832, 2016). "For instance, ZEB2, a 1.2 kb mRNA derives from a very long transcriptional unit that spans over 136 kb and is thought to be a tumor suppressor." (PMID 25798919, 2015). "Gene Set Enrichment Analysis using the top-500 probe sets overexpressed in immature/ETP-ALL patients, demonstrated that the gene expression profile of the Zeb2-overexpressing mouse tumours significantly overlapped with that of human immature/ETP-ALL patients." (PMID 25565005, 2015). "Consistent with ZEB2 as a tumor suppressor, several reports have documented down-regulation of ZEB2 mRNA in multiple cancers including those of brain, breast, colon, liver, skin, and pancreas." (PMID 25798919, 2015). "The current understanding of the EMT process is that transcription factors including SNAI1, SNAI2, ZEB1, ZEB2 and TWIST1 down-regulate CDH1 expression which subsequently results in the loss of cell adhesion and migration of tumor cells." (PMID 26214683, 2015). "In malignant tumor cells, Zeb2 and even other EMT-TFs are more stable, thus up-regulating the downstream oncogenic signals and triggering EMT and promoting cancer initiation, progression and development." (PMID 25460509, 2015). "The analysis of ZEB2 expression revealed that in the tumor edge the protein was mainly localized in the nucleus (continuous arrows), whereas in the inner part of the tumor the staining, if present, was restricted to the cytoplasm (dashed arrow)." (PMID 26136338, 2015). "The morphology of the cells in the leading edge was not different from the morphology of the cells in the inner mass of the tumors, nevertheless the sharp nuclear localization of ZEB2 in the tumor front suggested a commitment for the EMT process." (PMID 26136338, 2015). "Evaluation of ZEB2 and HuR was firstly focused on the localization within the cells (nuclear versus cytoplasmic) and in the tumor layers (core versus edge)." (PMID 26136338, 2015). "This nuclear localization strongly suggests that as a transcription factor ZEB2 exploited its regulatory activity on target genes specifically in the leading edge of the tumor, providing a commitment for the EMT process and an increased invasion ability." (PMID 26136338, 2015). "ISH experiments not only confirm the observed down-regulation of these RNAs in tumor, but also reveal that some of these transcripts, such as those deriving from ZEB2 introns, are down-regulated in epithelial tumor cells." (PMID 25798919, 2015). "This increase in cKit+ cells in the Zeb2 overexpression tumours was confirmed via immunohistochemistry." (PMID 25565005, 2015). "We next performed the multivariate regression analysis controlling for sex and tumor grade and found that both ZEB1 (p = 2.2 × 10−7) and ZEB2 (p = 0.006) were significantly associated with the expression levels of CD36 in the human protein samples." (PMID 26424075, 2015). "Rip2-deficient tumors showed enhanced epithelial-to-mesenchymal transition, with elevated expression of zeb1, zeb2, twist, and snail in the tumor microenvironment." (PMID 24733360, 2014).
tumor (continued). "It is evidenced that ZEB1 and ZEB2 expression is induced by a sudden changes in the tumor microenvironment such as varying oxygen tensions, exposing to ionizing radiation, contacting with chemotherapeutic agents, and or demethylating agents." (PMID 25197668, 2014). "In HPA study, 4/11 (36.4%) of RCC samples showed positive expression of ZEB2, and the immunoreactivity was mainly observed in the nuclei of the tumor cells." (PMID 23658743, 2013). "As expected, quantitative RT-PCR demonstrates elevated expression of both Snail and Zeb2 in the pTD cells (2-fold) and tumours (>4-fold) relative to the CDβGeo cells along with suppression of Sfrp1." (PMID 23883065, 2013). "The relevance of ZEB2 protein to tumor progression has been studied in several types of human cancers." (PMID 22393452, 2012). "The repression of these miRNAs coincides with publications showing that the down-regulation of miR-200 family contributes to metastasis of tumour cells by targeting ZEB1/ZEB2 and increasing E-cadherin." (PMID 22870299, 2012). "The relevance of ZEB2 to tumor progression has been studied in several forms of human cancer and it has been associated with various clinicopathological features such as histological type, differentiation grade, and overall survival." (PMID 22761708, 2012). "Strikingly, HCC patients with ZEB2 overexpression in both tumor and peritumoral tissues have the longest survival time among the subgroups of different ZEB2 expression status." (PMID 22393452, 2012). "In HCC tissues, further correlation analysis revealed that overexpression of cytoplasmic ZEB2 was significantly associated with serum AFP levels, tumor size and differentiation (P<0.05)." (PMID 22393452, 2012). "NP-siRNA-mediated knockdown of DCAMKL-1 resulted in upregulation of pri-miR-200a and downregulation of ZEB1 and ZEB2 with upregulation of E-cadherin in the HCT116 tumor xenografts." (PMID 21929751, 2011). "Regarding ZEB2, mRNA expression was decreased in tumor tissue while protein levels were elevated." (PMID 41481650, 2026). "Furthermore, we identified multiple, additional hallmarks of CACs harboring Mir34a-deficient myeloid cells, such as increased expression of Mmp9 in neutrophils and elevated expression of Zeb2 in an inflammatory subtype of CAC tumor cells." (PMID 39425000, 2025). "For example, in breast cancer, miR-205 inhibits EMT by specifically targeting ZEB1 and ZEB2, thereby exerting tumor suppressor effects; Whereas, in cervical cancer cells, up-regulation of miR-205 can significantly target and inhibit CHN1 expression levels, thereby promoting tumor cell proliferation." (PMID 41001034, 2025). "Based on the CDX mouse model, ZEB2 knockout TKI-resistant NSCLC tumor cells could upregulate M1 polarization and impede M2 polarization compared to the control group." (PMID 40510028, 2025). "Interestingly, ZEB2 is found at the invasive tumour front of CRC and induces EMT by matrix metalloproteinase (MMP) upregulation that can promote basement membrane breakdown, supporting cancer cell invasion." (PMID 40374531, 2025). "This phenomenon may be attributed to the expression of Zinc finger E-box-binding homeobox (ZEB2), a transcriptional repressor that initiates EMTs by downregulating E-cadherin expression, thereby enhancing tumor invasiveness." (PMID 40231252, 2025). "Restoration of ZEB2 expression can reverse the effects of CircZFR downregulation—such as cell cycle arrest and enhanced apoptosis—suggesting that this signaling axis plays a critical role in CircZFR-mediated tumor progression (W.-Y." (PMID 41158508, 2025). "In current research, gefitinib-resistant NSCLC tumor cells could induce M2 polarization and inhibit M1 polarization via ZEB2 upregulation." (PMID 40510028, 2025).
tumor (continued). "CD44, MMP-2, MMP-9, N-cadherin, and ZEB-2 were selected because they complementarily represent the three main axes of early tumor invasion: cell adhesion (CD44 and N-cadherin), extracellular matrix degradation (MMP-2 and MMP-9), and epithelial–mesenchymal transition (N-cadherin)." (PMID 40940940, 2025). "ZEB2 may be involved in promoting the development of NSCLC by rescuing the tumor inhibition effect of miR-1238." (PMID 38610009, 2024). "Taken together, these seemingly contradicting results suggest that PLEK and ZEB2 may show anti- or pro-tumor effects under different conditions which could be related to gene mutations and different cancer subtypes." (PMID 36969247, 2023). "Similarly, different EMT-TFs within the same family, such as ZEB1 and ZEB2, can have contrasting roles in tumor aggressiveness." (PMID 37444447, 2023). "ZEB2 expression is associated with a poor oncological prognosis and distant recurrence; hence, incorporating ZEB2 expression status into the tumor–node–metastasis (TNM) staging system facilitates the process of identifying patients who are at high risk of recurrence." (PMID 37834263, 2023). "ZEB2 suppresses the CDH1 to promote tumor cell invasion and chemo resistance." (PMID 37480054, 2023). "A previous study demonstrated that XIST promotes transforming growth factor-beta (TGF-β)-induced EMT which may regulate the miR-367/miR-141-ZEB2 axis in NSCLC, and our results showed that ZEB2 was highly expressed in the XIST+ tumor cells." (PMID 37430270, 2023). "Indeed, the HS578T-Hyg and M13HS tumor hybrids expressed ZEB2, whereby markedly higher ZEB2 levels were observed in the HS578T-Hyg ZEB1-KO cells as compared to the HS578T-Hyg wildtype cells." (PMID 38139138, 2023). "However, miR-30a, miR-3653, miR-138-5p, and miR-377 have been described as neoplasm suppressors using ZEB2 inhibition." (PMID 37174083, 2023). "Group 1 tumor spheroids are highly enriched for programs associated the epithelial–mesenchymal transition, KRAS signaling, and Myc activity and express high levels of the metastasis markers, such as Vimentin, TWIST1, and ZEB2." (PMID 37728504, 2023). "Regulatory mechanisms of TBX1 and the expression of ZEB1 and ZEB2 may differ among tumor types, organs, or species; however, the complete molecular mechanism underlying this effect is unknown." (PMID 36418889, 2022). "Thus, the study showed that a decrease in the expression level of miR-124 in the tumor increased the expression level of the ZEB2 gene, followed by the launch of EMT and the development of metastases." (PMID 36362406, 2022). "Taken together, our findings suggest that ZEB2 could be a potential prognostic biomarker and may provide novel insights into tumor immunology." (PMID 35723302, 2022). "Indeed, mRNA and protein expression levels of an epithelial gene (CLDN1) were decreased, while those of mesenchymal (VIM) and EMT regulator (Snail, Twist1, ZEB1, and ZEB2) genes were increased in tumor cells." (PMID 35618735, 2022). "Mechanistically, TGF-β enhances pSMAD2/3 and ZEB1 and ZEB2 expression to increase tumour invasion." (PMID 36499447, 2022). "Additionally, honokiol-treated animals exhibited decreased ZEB2, vimentin and fibronectin levels and increased E-cadherin levels in tumor tissues compared to the control." (PMID 35805049, 2022). "It was found that honokiol suppressed proliferation and migration of the A-498 cell line by dual-blocking the epithelial–mesenchyme transition and reversing the miR-141/zing finger E-boc binding homebox 2 (ZEB2) axis, a tumor suppressor that is downregulated in RCC." (PMID 35805049, 2022). "Zinc finger E-box binding homeobox (ZEB) family homeodomain transcription factors, such as ZEB1 and ZEB2, play a pivotal role in tumour progression and metastasis by induction epithelial-mesenchymal transition (EMT), with activation of stem cell traits, immune evasion and epigenetic reprogramming." (PMID 36499447, 2022).